ERCC1 (ERCC excision repair 1, endonuclease non-catalytic subunit)
Diseases named in the same sentence as ERCC1 in open-access papers (continued):
Sharing a sentence is not in itself a finding about the gene and the disease.
breast carcinoma (continued). "We believe that ERCC1 could serve as a target for personalized treatment of breast cancer, especially for TNBC." (PMID 30096175, 2018). "Despite the fact that a mounting body of case–control studies has concentrated on investigating the association of the ERCC1 rs11615 polymorphism and breast cancer risk, there is still no consensus on it." (PMID 29752341, 2018). "We found that the genotypes of ERCC1 rs11615 were associated with breast cancer susceptibility, while rs3212986 polymorphism was not." (PMID 30096175, 2018). "Risk of FAC-related anemia of any grade was elevated by polymorphic allele C of p.Asn118= (rs11615) variant in ERCC1 gene, common homozygote GG of ABCC2 p.Val417Ile (rs2273697) polymorphism, presence of both GSTT1 and GSTM1 genes and triple-negativity of breast cancer." (PMID 29507678, 2018). "Our results indicated that genotypes of ERCC1 rs11615 (Ptrend = 2.2*10E-9), but not rs3212986 (Ptrend = 0.6181), were associated with breast cancer risk." (PMID 30096175, 2018). "Besides, ERCC1 rs11615 (T allele), and ERCC2/XPD rs50872 (T allele) were associated with postmenopausal breast cancer, while XPC rs2228000 (T allele) was associated with premenopausal breast cancer." (PMID 27768589, 2016). "ERCC1/CYP1B1 combination might be of particular interest to predict response to NCT in breast cancer and particularly to help NCT indication for ER+ breast tumors." (PMID 26180747, 2015). "Moreover ERCC1/CYPB1 combination appeared to be a potential predictive marker to guide NCT indication in breast cancer and particularly for ER+ breast tumors." (PMID 26180747, 2015). "Multivariate analysis revealed that ERCC1 (Asn118Asn) combined to CYP1B1 (Leu432Val) might be of particular interest as predictive markers for NCT in breast cancer." (PMID 26180747, 2015). "The ERCC1 8092A and 19007C genotypes or their combination may predict a favorable prognosis in T4 breast cancer patients undergoing a platinum-based treatment." (PMID 25253066, 2014). "Thus, we processed a serial studies about ERCC1 in breast cancer and look for novel anti-cancer strategies to avoid drug resistance and improve treatment outcomes." (PMID 23046742, 2012). "ERCC1 might have its roles in DNA repair systems in breast cancer, but its contribution to drug resistance remains unclear." (PMID 23046742, 2012). "Excision repair cross complementation group 1 (ERCC1) protein encoded by ERCC1 gene is a key player in nucleotide excision repair (NER), and our previous work and others have demonstrated that this protein is also expressed in breast cancer." (PMID 23046742, 2012). "However, the mechanism of the effect of PARP1, XRCC4 and ERCC1 on the metastasis of breast cancer remains unclear, which needs further study (Fig. S1A1)." (PMID 33184404, 2020). "The purpose of our study was to explore the associations between ERCC1/XPF polymorphisms and breast cancer risk and to compare their distributions in Uygurs and Hans to improve our understanding of their roles in the pathogenesis of breast cancer in different races." (PMID 33067872, 2020). "ERCC1 based stratification could be an attractive strategy in breast cancers." (PMID 31405143, 2019). "Therefore, ERCC1 rs11615 genotypes may serve as predictive markers for the early detection of breast cancer patients." (PMID 30096175, 2018). "Interestingly, Zhu and his colleagues showed that there were no statistical associations between ERCC1 rs11615 and the risk of breast cancer." (PMID 30096175, 2018). "The correlation between ERCC1 expression, patient prognosis, and clinicopathological features is still unclear in patients with HER2-positive breast cancer." (PMID 36338712, 2022).
breast carcinoma (continued). "ERCC1 and XPF siRNA depletion was previously shown to increase cisplatin sensitivity in non-small lung and breast cancer cells." (PMID 31405143, 2019). "Our findings indicate that the representation of the ERCC1 rs11615 TT genotype was increased by about 10% (from 15% to 25%) among the patients with TNBC, compared with other breast cancer patients." (PMID 30096175, 2018). "Overall anemia (grade 1–2) high risk genetic factors belonged to all three functional groups – DNA repair (ERCC1, p.Asn118=), metabolism (GSTT1 and GSTM1 present) and transport (ABCC2, p.Val417Ile), with addition of breast cancer triple negativity." (PMID 29507678, 2018). "In this study, 1,232 breast cancer patients (104 were TNBC) and 1,232 healthy controls were recruited and their genotypes at ERCC1 rs11615 and rs3212986 were revealed by polymerase chain reaction restriction fragment length polymorphism (PCR-RFLP) analysis." (PMID 30096175, 2018). "In 2015, Dumont and his colleagues proposed that the genotypes of ERCC1 rs11615 and CYP1B1 rs1056836 can jointly predict the prognosis responses to neoadjuvant chemotherapy of breast cancer patients, especially ER positive ones." (PMID 30096175, 2018). "This study is the first to report ERCC1, BRCA1 and SLCO1B3 as markers of response to NCT in breast cancer." (PMID 26180747, 2015). "Thus, many studies have shown that the expression and/or co-expression of several genes, such as ERCC1, RRM1, TOP1, TOP2α, TUBB3, TYMS, and GSTP1, in tumor tissues is closely related to chemoresistance and prognosis in breast cancer patients (BC)." (PMID 35204496, 2022). "Therefore, it is necessary to explore the ERCC1expression pattern to determine the effect of ERCC1 expression on the clinicopathological features and prognosis of patients with HER2-positive breast cancer treated with trastuzumab." (PMID 36338712, 2022). "Moreover, ERCC1 expression and vascular tumor thrombus are independent prognostic factors influencing OS in patients with HER2 over-expressing breast cancer." (PMID 36338712, 2022). "As determined by a chi‐squared test, the distributions of ERCC1 rs2298881 C>A (p < 0.001), ERCC1 rs11615 G>A (p < 0.001), and XPF rs2276466 C>G (p = 0.002) differed significantly between Uygur and Han patients with breast cancer." (PMID 33067872, 2020). "Arguably, cancer-related effects of variations in ERCC2 may be influenced by variations in ERCC1, so both of the ERCC genes should be evaluated for genetic variation related to breast cancer." (PMID 19208188, 2009). "Similarly, ERCC1 and ERCC2 expression levels were significantly correlated (r = 0.61, p-value = 2 × 10−5, n = 75) in triple negative, but not correlated (r = − 0.10, p-value = 5 × 10−1, n = 68) in luminal A Breast cancer patients." (PMID 34837938, 2021). "However, due to the limited experimental samples, the relationship between the methylation status of ERCC1 and breast cancer could not be explored in this study and will be investigated by us in future studies." (PMID 36338712, 2022).
breast carcinoma (continued). "The identification of ERCC1 genotypes among Taiwanese individuals without cancer and those who suffer from breast cancer may lead to a better understanding of the mechanisms behind breast cancer." (PMID 30096175, 2018). "A negative correlation was observed between ERCC1 and ER expression in patients with HER2 over-expressing breast cancer." (PMID 36338712, 2022). "Our results show a significant negative correlation between ERCC1 expression and CD8+ T cells in patients with HER2 over-expressing breast cancer." (PMID 36338712, 2022). "ER, HER2, E-Cad, Ki67, Molecular subtypes, XRCC1, XRCC4, 53BP1, ERCC1 and XPA were not independent prognostic factors of postoperative breast cancer metastasis (P > 0.05)." (PMID 33184404, 2020). "In addition, as the gene sensitive to cisplatin or other DNA damaging agents, expression of ERCC1 is closely related to BRCA1, no matter in breast cancer or in NSCLC." (PMID 22439756, 2012). "However, a negative correlation was observed between ERCC1 expression and HRD in patients with breast cancer, thereby suggesting that ERCC1 expression may influence the efficacy of chemotherapy on patients with breast cancer." (PMID 36338712, 2022).
xeroderma pigmentosum (46 papers, 2009 to 2025). Xeroderma pigmentosum (XP) is a rare genodermatosis characterized by extreme sensitivity to ultraviolet (UV)-induced changes in the skin and eyes, and multiple skin cancers. "The ERCC4 i.e. excision repair cross-complimentary group 4 gene forms a complex with ERCC1 to encode the two subunits of the ERCC1-XPF (xeroderma pigmentosum complementation group F) nuclease." (PMID 34079756, 2021). "Compared to the DON group and the HO-1shRNA group, the expression of excision repair cross-complementation group 1 (ERCC1) and xeroderma pigmentosum complementation group C (XPC) in the mouse liver of the HO-1OE group was much increased." (PMID 34679025, 2021). "Mutations within ERCC1 or XPF cause increased risk of cancer, XFE progeroid syndrome, xeroderma pigmentosum (XP), or cerebro-oculo-facio-skeletal syndromes characterized by accelerated aging along with developmental abnormalities." (PMID 32526825, 2020). "A key cellular factor that contributes to sensitivity to platinums is the 5′-3′ structure-specific endonuclease excision repair cross-complementation group 1 (ERCC1)/ xeroderma pigmentosum group F (XPF)." (PMID 32344513, 2020). "Excision repair cross-complementary 1 (ERCC1) is a key protein involved in the process of NER and ERCC1-xeroderma pigmentosum (ERCC1-XPF) catalyzes incision on the incision 50 side to the site of DNA damage." (PMID 25452763, 2014). "Further, the expression of ERCC1 and XPA (xeroderma pigmentosum group A) demonstrated that ERCC1 expression was predictive of oxaliplatin sensitivity." (PMID 22276017, 2009). "During DNA repair processes, excision repair cross-complementation group 1 (ERCC1) and xeroderma pigmentosum complementation group F (XPF) proteins form a heterodimer with endonuclease activity, which catalyzes the incision at the 5’-side of the damaged DNA strand." (PMID 39339159, 2024). "Xeroderma pigmentosum patients belonging to the XPF complementation group have reduced cellular levels of both XPF and ERCC1 and, conversely, ERCC1-deficient cells show low levels of XPF, implying that formation of the heterodimeric complex stabilises both proteins in vivo." (PMID 28903417, 2017). "ERCC1-XPF, the human homolog of yeast Rad10-Rad1, is a structure-specific endonuclease that makes a 5′-incision in the damaged DNA strand during NER, and its deficiency causes an inherent genetic disease, xeroderma pigmentosum." (PMID 27294910, 2016). "Using the chemically synthesized oligonucleotides, we investigated the excision of the 3′-CTNAs in DNA by the human excision repair cross complementing protein 1-xeroderma pigmentosum group F (ERCC1-XPF) endonuclease, which is one of the main components of the nucleotide excision repair pathway." (PMID 27294910, 2016). "The xeroderma pigmentosum (XP) proteins, along with excision repair cross-complementation group 1 (ERCC1), both play essential roles in the NER pathway." (PMID 39044839, 2024). "The NER process needs the participation of many proteins, such as Xeroderma pigmentosum (XP) complementation Groups A through G, excision repair cross-complementation group 1 (ERCC1), and proliferating cell nuclear antigen (PCNA)." (PMID 31546657, 2019). "Preclinical studies targeting several enzymes within the NER pathway, including excision repair cross-complementation group 1/xeroderma pigmentosum group F (ERCC1/XPF) and ERCC1/XPA, have demonstrated anti-tumor activity." (PMID 38730598, 2024). "Excision repair cross-complementing group 1 (ERCC1), one of the NER mediators, and its catalytic partner, xeroderma pigmentosum group F (XPF, ERCC4), have been demonstrated to be closely related with Ox resistance." (PMID 36978904, 2023). "Biallelic pathogenic variants in one of the seven NER genes coding for the so-called complementation groups, XPA, ERCC3, XPC, ERCC2, DDB2, ERCC4, ERCC5, the NER gene ERCC1, and the gene coding for XP variant, POLH, are the causes of the rare hereditary disease Xeroderma pigmentosum (XP)." (PMID 35174087, 2022).
xeroderma pigmentosum (continued). "Both edges of the damaged strands are cut by endonuclease activity of XPF/ERCC1 (xeroderma pigmentosum complementation group F/Excision repair crosscomplementation group 1) and XPG (xeroderma pigmentosum complementation group G) proteins." (PMID 34377049, 2021). "In mammalian cells, null mutants of the ERCC1 or XPF genes are lethal and weaker mutations can result in xeroderma pigmentosum (XP), trichothiodystrophy (TTD), and Cockayne syndrome (CS), genetic disorders that are typical of mutations in genes required for NER." (PMID 31143199, 2019). "The two major genes involved in the NER pathway are excision repair cross-complementation group 1 (ERCC1) and xeroderma pigmentosa." (PMID 27563673, 2016). "Together with ERCC4 (xeroderma pigmentosum group F, XPF), ERCC1 forms a structure-specific endonuclease which plays a rate-limiting role in the nucleotide excision (NER) pathway that recognizes and removes DNA adducts that are formed during cisplatin treatment." (PMID 32344513, 2020). "ERCC1 and ERCC2 (xeroderma pigmentosa—XPD) are the two major genes involved in this pathway." (PMID 22276017, 2009).
progeria (29 papers, 2008 to 2025). "Mice deficient in Ercc1 have been extensively studied due to the accelerated aging phenotype modeling a human progeroid syndrome and have been shown to be a powerful system for identifying health-sustaining interventions." (PMID 33493548, 2021). "We demonstrated previously that NF‐κB transcriptional activity is upregulated in tissues from both natural aged mice and in a mouse model of a human progeroid syndrome caused by defective repair of DNA damage (ERCC1‐deficient mice)." (PMID 28229533, 2017). "Here, we reveal a significant common transcriptomic signature in livers from hypothyroid mice, DNA repair-deficient mice with severe (Csbm/m/Xpa-/-) or intermediate (Ercc1-/Δ-7) progeria and naturally aged mice." (PMID 26953569, 2016). "We have used a progeroid model of endogenous DNA damage accumulation to identify miRNA dysregulation common to both the Ercc1-deficient mouse model of progeria and normal mouse aging in liver and kidney tissues." (PMID 23852002, 2013). "Herein we show that several downregulated miRNAs in the ERCC1-deficient mouse model of progeria are also down-regulated during normal murine aging." (PMID 23852002, 2013). "We demonstrated previously that NF‐κB transcriptional activity is upregulated stoichastically in a variety of tissues with both natural aging and in a mouse model of a human progeroid syndrome caused by defective repair of DNA damage, Ercc1−/∆ hypomorphic mouse." (PMID 28229533, 2017). "The Ercc1−/Δ and Xpg−/− mice used in this study both present multisystem progeria phenotypes that compromise longevity and involve the early onset of complex age-related pathologies characteristic of accelerated biological aging." (PMID 38987495, 2025). "Ercc1Δ/− mice, a progeria model with a truncated version of ERCC1 in all cells, display tubular degeneration and necrosis." (PMID 41004128, 2025). "For example, the ERCC1 knockout mouse model depletes the enzyme responsible for multiple DNA repair mechanisms that protect the nuclear genome, resulting in progeria disease progression." (PMID 40936799, 2025). "Like HGPS patients, the ERCC1 knockout progeria model exhibits impaired vascular function even at young ages." (PMID 40936799, 2025). "Both the mSFI and CFI were applied in male (N = 4) and female (N = 4) Ercc1−/Δ mice as well as male (N = 4) and female (N = 4) ERCC1 wt mice at 8 weeks of age to anticipate the rapid physical decline observed in these progeria models." (PMID 38987495, 2025). "Our recent studies of Z24−/− and ERCC1-/delta progeria mice revealed that NF-κB inactivation is an effective way in rescuing the senescent phenotypes of the mice." (PMID 39039044, 2024). "This study investigated the cardiac effects of progeria induced by attenuated levels of Ercc1, which is required for DNA excision and repair, and the impact of activin signalling blockade using a soluble activin receptor type IIB (sActRIIB)." (PMID 35380160, 2022). "Multiple progeria mouse models, such as Zmpste24−/−, Ercc1−/−, and aP2‐cre; Ercc1fl/−, have been shown to exhibit reduced fat depots similar to naturally aged WT mice." (PMID 34734460, 2021). "For example, the Ercc1 null mouse has been used as a model of accelerated aging (progeria) because it exhibits shunted growth, wasting, ataxia, and premature death by 1-2 months of age." (PMID 23095216, 2012). "However, mutations that inactivate ERCC1-XPF catalytic function or abrogate the XPG protein cause different types of neurological deficiencies, progeria, and severe developmental failure, often resulting in early death, that resemble Cockayne syndrome." (PMID 38664429, 2024). "Ercc1-/Δ mice model a human progeroid syndrome, aging rapidly between 2-6 months of life." (PMID 30745468, 2019). "That age‐dependent increase was accelerated in Ercc1−/Δ and Bubr1H/H mouse models of progeria." (PMID 29290100, 2018).
progeria (continued). "In addition, the Xpg−/− mouse model shows a number of similarities to other NER-based mouse models of progeria such as Xpa/Csb and Ercc1 mutants, pointing to the importance of NER in multiple tissues." (PMID 25299392, 2014). "As expected, based on the multi-system physiological consequences of their progeria phenotype, Ercc1−/Δ mice showed parallel significant increases in CFI values compared to Ercc1 wt." (PMID 38987495, 2025). "To examine the ability of SR12343 to suppress markers of senescence and aging in vivo, we initially utilized the Ercc1−/Δ mouse, a model of accelerated aging that mimics human XFE progeria." (PMID 34734460, 2021). "Rare mutations in ERCC1 and ERCC4/XPF, encoding the NER 5’-endonuclease, may cause complicated features beyond XP, CS, and TTD, including Cerebro-Oculo-Facio-Skeletal Syndrome (COFS), Fanconi anemia (FA), XFE-progeroid syndrome (XFE), XP-CS-FA, and ERCC1-hepatorenal syndrome." (PMID 40924495, 2025).